FAM228B (family with sequence similarity 228 member B)
Tractability: No criterion of Open Targets' tractability assessment is met for any kind of drug.
Gene: Protein-coding gene on chromosome 2 (24,076,526 to 24,169,642, forward strand). Ensembl gene ENSG00000219626.
Subcellular location (Human Protein Atlas): Golgi apparatus
Genetic constraint (gnomAD): Loss-of-function variants: 18 observed, 19.41 expected, observed/expected ratio (o/e) 0.93, 90% interval 0.64 to 1.38. The upper end of that interval is the gene's LOEUF score, 1.38, which puts it in group 5 of 6, group 1 being the genes least tolerant of losing a copy. Missense variants: 190 observed, 209.75 expected, observed/expected ratio (o/e) 0.91, 90% interval 0.8 to 1.02. Synonymous variants: 59 observed, 73.4 expected, observed/expected ratio (o/e) 0.8, 90% interval 0.65 to 1.
Homologues: Orthologues: chimpanzee FAM228B (99% identical), macaque FAM228B (83% identical), rabbit FAM228B (74% identical), rat Fam228b (68% identical), pig FAM228B (68% identical), mouse Fam228b (56% identical), guinea pig FAM228B (53% identical), tropical clawed frog fam228b (28% identical), zebrafish fam228a (19% identical). Paralogues in human: FAM228A (20% identical).
Diseases named in the same sentence as FAM228B in open-access papers:
FAM228B is named in the same sentence as 2 diseases in open-access papers, as found by Europe PMC text mining. Sharing a sentence is not in itself a finding about the gene and the disease. The quoted sentences say what the papers report.
epilepsy (1 paper, 2023). A brain disorder characterized by episodes of abnormally increased neuronal discharge resulting in transient episodes of sensory or motor neurological dysfunction, or psychic dysfunction. "FAM228B has been linked to mental health issues, ZNF566 to cardiovascular diseases, and SPIRE2 to cardiovascular diseases and epilepsy." (PMID 38681774, 2023).
FAM228B also shares sentences with these, for which no sentence is quoted: cardiovascular diseases (1 paper).